PTH (parathyroid hormone)
Diseases named in the same sentence as PTH in open-access papers (continued):
Sharing a sentence is not in itself a finding about the gene and the disease.
Nephropathy (9 papers, 2013 to 2025). A nonspecific term referring to disease or damage of the kidneys. "Resveratrol, with the property of reducing oxidative stress-mediated renal injury in the animal model of nephropathy, can inhibit PTH induced apoptosis and restore bcl-2 expression as a sirtuin 1 agonist." (PMID 35166167, 2022). "Mice developed histological, serological, and functional evidence of kidney damage, decreased GFR, increased expression of kidney injury and fibrosis markers, and significantly increased levels of PTH and FGF23 compared with animals fed a control diet." (PMID 39688907, 2024).
papillary thyroid cancer (9 papers, 2015 to 2026). "A presumed role for PTH excess in triggering the onset of papillary thyroid cancer remains controversial." (PMID 33957725, 2021). "The purpose of this study was to investigate parathyroid hormone (PTH), serum calcium, phosphorus, and 25-hydroxyvitamin D (25-OH-VD) changes before and after radioactive iodine (RAI) in differentiated thyroid carcinoma (DTC) patients at different time points." (PMID 34122347, 2021). "Thus, the purpose of this study was to investigate PTH, serum calcium, phosphorus, and 25-OH-VD changes after RAI in patients with differentiated thyroid carcinoma (DTC) at different time points." (PMID 34122347, 2021). "Eleven lesions with negative PTH-WO results but suspicious for PA on imaging findings were cytologically (three) and pathologically (eight) confirmed not to be PA, benign lymph nodes (n = 6), benign thyroid nodules (n = 4), and papillary thyroid cancer (n = 1)." (PMID 37745742, 2023).
periodontal disease (9 papers, 2016 to 2025). "Our results provided evidences for applications of PTH in stem cell therapy for periodontitis diseases." (PMID 27069479, 2016). "Therefore, we will discuss the relationship between periodontal disease and serum levels of calcium, phosphorus, alkaline phosphatase, and PTH in patients with HD." (PMID 31382656, 2019). "Finally, the authors speculated that secondary hyper-parathyroidism and increased serum PTH levels played minimal roles in periodontal disease and periodontal indices in HD patients, a speculation that we also find plausible." (PMID 31382656, 2019). "Thus, PTH could also be involved in the development of periodontal disease." (PMID 35582348, 2022). "Taken together, the findings revealed the role and mechanism of PTH and JNK pathway in promoting the osteogenic differentiation of LPS-induced HBMSCs, which offered an alternative for treating periodontal diseases." (PMID 34350461, 2021).
peritonitis (9 papers, 2016 to 2025). Inflammation of the peritoneum (tissue that lines the abdominal wall and covers most of the organs in the abdomen). "There is limited evidence on the impact of the parathyroid hormone (PTH) on the first peritoneal dialysis (PD)-associated peritonitis episode." (PMID 37051200, 2023). "Low PTH levels (< 150 pg/mL) were significantly associated with a 1.643-fold increased risk of peritonitis incidence [HR 1.643 (95%CI 1.014–2.663), P = 0.044]." (PMID 33514340, 2021). "After multivariate adjustment, lower PTH levels were identified as an independent risk factor for peritonitis episodes [hazard ratio 1.643, 95% confidence interval 1.014–2.663, P = 0.044]." (PMID 33514340, 2021). "This study was carried out to estimate the association of serum PTH levels with PD-related peritonitis." (PMID 33514340, 2021). "The association between the variation of PTH levels, vitamin D therapy and peritonitis episodes need more studies searched." (PMID 33514340, 2021). "Only “low PTH + high Ca” and “low PTH + low (or normal) P” are significantly associated with higher risk of experiencing the first episode of peritonitis." (PMID 33441921, 2021). "We examined the association of PTH levels and peritonitis incidence in a 7-year cohort of 270 incident PD patients who were maintained on dialysis between January 2012 and December 2018 using Cox proportional hazard regression analyses." (PMID 33514340, 2021). "The present study demonstrates that low PTH levels are independently associated with a higher risk of peritonitis incidence in incident PD patients." (PMID 33514340, 2021). "This present study demonstrated that lower baseline PTH levels were associated with a greater risk of peritonitis." (PMID 33514340, 2021). "After adjusting for age, sex and serum albumin levels, we found that the combinations of low PTH levels with either high Ca levels or low/normal P levels were significant risk factors of developing peritonitis." (PMID 33441921, 2021). "Further analysis of potential synergistic effects of these three biochemical markers demonstrated that low PTH/high Ca, low PTH/low P or high Ca/low P were associated with the worst peritonitis-free survival outcomes." (PMID 33441921, 2021). "Thus far, to the best of our knowledge, there are only a few existing cohort studies that attempted to understand the associations between serum PTH and peritonitis in patients undergoing PD." (PMID 37051200, 2023). "A cohort study that included 270 patients who had PD revealed that, after adjusting for limited confounders, the multivariate analysis showed that lower serum PTH levels (with 150 pg/ml as a category) were independently associated with peritonitis in incident PD patients." (PMID 37051200, 2023). "We hypothesized that lower PTH might be associated with higher incidence rate of peritonitis in PD patients." (PMID 33514340, 2021). "A study of 748 dialysis patients implicated that PTH < 150 pg/mL was associated with elevated inflammatory markers, including tumor necrosis factor α and C-reactive protein, which were traditional evaluated parameters for peritonitis." (PMID 33514340, 2021). "In conclusion, this registry-based observational study has demonstrated for the first time that the combination of low PTH and high Ca or low P could be a potential risk factor for peritonitis occurrence." (PMID 33441921, 2021). "Low PTH levels are independently associated with peritonitis in incident PD patients." (PMID 33514340, 2021). "Herein, we hypothesize that PD patients with deranged PTH would exert immune dysregulation to different extent, which may lead to increased or decreased risk of developing peritonitis." (PMID 33441921, 2021). "However, there are still no definitive accepted explanations on whether increased or decreased PTH levels in patients undergoing PD increase the occurrence of peritonitis risk, and the underlying possible pathophysiological mechanisms are still unclear." (PMID 37051200, 2023).
peritonitis (continued). "Whether PTH is associated with peritonitis episodes remains unclear." (PMID 33514340, 2021). "However, when analyzing data based on the paired combinations, low PTH + high Ca (HR = 1.269) as well as low PTH + normal P (HR = 1.187) or low PTH + low P (HR = 1.541) were significantly associated with the early experience of PD-related peritonitis in this cohort." (PMID 33441921, 2021). "Both groups had similar clinical characteristics except significantly higher levels of BP, serum calcium, serum parathyroid hormone, peritonitis episodes, and less use of erythropoietin-stimulating agent in the App group." (PMID 40397925, 2025). "Peritonitis-free survival and the influence of PTH, Ca, P (individual or in combination) on the peritonitis occurrence were analysed." (PMID 33441921, 2021). "Future large-scale studies should afford insights for understanding the potential mechanisms how PTH levels predict peritonitis incidence." (PMID 33514340, 2021). "Meanwhile, 25 (9.3%) patients had relapsed peritonitis, and patients in low-PTH group had the highest incidence rate of relapsed peritonitis (16.7% vs 10.1% vs 4.1%, P = 0.000)." (PMID 33514340, 2021). "To further examine whether abnormal serum PTH/Ca/P levels at baseline are potential risk factors for the development of PD-related peritonitis, we carried out univariate and multivariate Cox proportional regression models based on the time of PD start to the first episode of peritonitis." (PMID 33441921, 2021). "The overall incidence rate of peritonitis was 0.10 episodes/patient-year, the patients with low PTH levels had significantly more peritonitis [0.18 vs 0.07 vs 0.06 episodes/person-year, respectively (P = 0.000)] than those with middle, high PTH levels." (PMID 33514340, 2021). "This study found that low dialysate calcium was superior to the standard dose in decreasing serum total calcium levels in PD patients, while the effects on i-PTH levels and peritonitis episodes remain controversial." (PMID 31185931, 2019). "In this study, we found that the predominant causative organism of peritonitis patients with low PTH levels was Gram-negative organism, especially Esherichia coli." (PMID 33514340, 2021). "The pathophysiologic mechanisms, how low PTH levels increase the susceptibility of peritonitis incidence in PD patients, are not still well explained." (PMID 33514340, 2021). "On the one hand, the impairment of the immune system in PD patients leads to an increased incidence of infections, and PTH plays an important role in the long-term immunodeficient and inflammation state, which is the main contributor to the peritonitis episodes." (PMID 33514340, 2021). "Thus, we will examine the relationships between baseline serum PTH (as well as calcium, phosphorus) and the occurrence of first episode of peritonitis in ESKD patients undergoing maintenance PD, based on a nationwide dialysis registry cohort in Taiwan." (PMID 33441921, 2021). "And, we demonstrated the relationship between PTH and incidence of peritonitis in PD patients." (PMID 33514340, 2021). "Interestingly, further analysis of paired combination data (“PTH + Ca”, “PTH + P”, “Ca + P”) revealed that “low PTH + high Ca”, “low PTH + low P”, or “high Ca + low P” has the worst peritonitis-free survival among the nine pairs in each combinational dataset, respectively." (PMID 33441921, 2021). "Abnormal mineral bone metabolism in maintenance PD patients with low serum PTH levels, in combination with either high Ca levels or low/normal P levels, could be novel risk factors of PD-related peritonitis." (PMID 33441921, 2021). "However, it is unclear whether the disordered PTH is related to the occurrence of PD-related peritonitis in incident PD patients." (PMID 33441921, 2021). "Therefore, we suspect that low serum PTH levels may play a role in incidence of PD-related peritonitis." (PMID 33514340, 2021).
peritonitis (continued). "To explore the potential impact of aberrant serum PTH/calcium/phosphorus levels (individual or combined effects) on the occurrence of PD-related peritonitis, we longitudinally followed up these patients for 60 months and analyzed their peritonitis-free survivals for comparisons." (PMID 33441921, 2021). "Odds ratios or standardized mean differences were used to assess the outcome measures, including intact parathyroid hormone (i-PTH) levels, serum total calcium amounts, ionized calcium levels, phosphate concentrations, and peritonitis episodes." (PMID 31185931, 2019). "Thirdly, the summary results for i-PTH and peritonitis episodes were obtained, which was not the case in the previous meta-analysis." (PMID 31185931, 2019).
acrodysostosis (8 papers, 2017 to 2025). Acrodysostosis (ACRDYS) is a rare primary bone dysplasia characterized by severe brachydactyly, peripheral dysostosis with facial dysostosis, nasal hypoplasia, and developmental delay. "Acrodysostosis is another rare genetic disorder which is associated with PTH resistance." (PMID 31856822, 2019). "Hormone resistances, usually PTH and/or TSH resistance, have been detected in about 60-70% of acrodysostosis patients with a PRKAR1A mutation and in 10-20% of cases with PDE4D mutations." (PMID 29280743, 2017). "PTH resistance and brachydactyly (but in a more severe form) are also present in acrodysostosis with multihormonal resistance ACRDYS1 (or iPPSD4, OMIM#101800), which is associated with mutations in the gene coding for the cAMP-dependent protein kinase type 1 regulatory subunit protein (PRKAR1A)." (PMID 29499646, 2018). "Acrodysostosis (OMIM - #101800) refers to a group of rare skeletal dysplasias that present features typical of PHP, such as resistance to PTH, TSH, and severe brachydactyly." (PMID 40444234, 2025). "Although these two diseases, acrodysostosis and HTNB syndrome exhibit molecular defects in the PTH-cAMP pathway and are clinically identical to PHP/pPHP, they were not previously included in the classification of PHP." (PMID 29280743, 2017). "The European Network for the study of PHP (EuroPHPnetwork) in 2016 suggested using new nomenclature inactivating PTH/PTHrP signaling disorder (iPPSD) instead of e.g. PHP and PPHP, POH, Acrodysostosis to refer to common pathogenesis of impairments in PTH and/or PTHrP cAMP-mediated pathway." (PMID 40444234, 2025). "Other symptoms might also be present in patients with acrodysostosis, such as cognitive impairment, being born SGA and resistance to PTH and/or other hormones that signal through Gsα6,13,15,63,64." (PMID 29959430, 2018). "Acrodysostosis (OMIM #101800) refers to a group of chondrodysplasias that resemble PHP in some patients, owing to the presence of brachydactyly and often resistance to PTH and TSH, but differ from PHP owing to more extensive facial dysmorphism, nasal hypoplasia and often developmental delay." (PMID 29959430, 2018).
acromegaly (8 papers, 2013 to 2023). Acromegaly is an acquired disorder related to excessive production of growth hormone (GH) and characterized by progressive somatic disfigurement (mainly involving the face and extremities) and systemic manifestations. "Correlations between PTH and vitamin D and diagnostic parameters for acromegaly are available in Appendix A (Table A1)." (PMID 38137499, 2023). "The association of acromegaly with PTH and 25(OH)D levels remains unclear." (PMID 35340319, 2022). "In patients with acromegaly, although there are increases in 1,25-dihydroxyvitamin D (25[OH]D) levels, data on 25(OH)D and parathormone (PTH) are contradictory." (PMID 35340319, 2022). "Age, gender, BMI, creatinine, eGFR, ALT, magnesium, PTH, and 25(OH)D levels were similar in patients with active acromegaly and those in remission." (PMID 35340319, 2022). "In the present study, 25(OH)D and PTH levels were similar between acromegaly patients and healthy controls, as in between patients with active disease and patients with controlled disease." (PMID 35340319, 2022). "Age, estimated glomerular filtration rate (eGFR), PTH, and 25(OH)D levels were similar in the acromegaly group and the control group." (PMID 35340319, 2022). "While calcium and phosphorus levels were higher in patients with acromegaly than in healthy controls, as in the literature, we found similar PTH and 25(OH)D levels in these groups." (PMID 35340319, 2022). "Age, gender, BMI, creatinine, eGFR, PTH, and 25(OH)D levels were similar in the acromegaly group and the control group." (PMID 35340319, 2022). "Acromegaly and control groups, as well as active/controlled acromegaly groupswere compared in terms of alkaline phosphatase (ALP), calcium, magnesium, phosphorus, parathormone (PTH) and 25-OH Vitamin D (25[OH]D), and C-terminal telopeptide of type 1 collagen (CTX)." (PMID 35340319, 2022).
atrial fibrillation (8 papers, 2014 to 2023). A disorder characterized by an electrocardiographic finding of a supraventricular arrhythmia characterized by the replacement of consistent P waves by rapid oscillations or fibrillatory waves that vary in size, shape and timing and are accompanied by an irregular ventricular response. "Higher PTH concentrations (Q2–Q4) were significantly and incrementally associated with an increased prevalence of atrial fibrillation in this patient group." (PMID 34170509, 2021). "A recent multicentre prospective cohort study from the Fukuoka Kidney Disease Registry (3,384 non-dialysis CKD patients) explored the relationship between PTH concentrations and the prevalence of atrial fibrillation." (PMID 34170509, 2021). "A 71-year-old man with known history of atrial fibrillation (treated with routine rivaroxaban therapy) was found to have incidental biochemical elevated calcium and parathyroid hormone (PTH) levels." (PMID 30425877, 2018). "In addition, increased blood calcium and parathyroid hormone levels and dysfunction of sympathetic nervous system have been indicated in abnormal bone remodeling, low BMD and pathogenesis of atrial fibrillation (AF)." (PMID 34515906, 2021).
bone tumors (8 papers, 2016 to 2025). "A prolonged treatment period and high administration dose of recombinant human parathyroid hormone (teriparatide) increases the incidence of bone neoplasms." (PMID 36794024, 2022). "Our model suggests that whether or not the patient has an impaired PTH circadian rhythm should also be investigated in order to avoid increasing bone loss or at the other extreme to increase the risk of bone tumors." (PMID 27379013, 2016).
brachydactyly (8 papers, 2018 to 2024). A disease characterized by the presence of brachydactyly, including syndromic and non-syndromic forms. "So, as the clinical implications may be different depending on the parental origin of the variant, and some of them as PTH resistance and brachydactyly evolves with time, parental testing is indicated when a genetic alteration is detected." (PMID 36686455, 2022). "Of the 22 GNAS mutations detected in GOOS participants, 5 had brachydactyly and 2 had evidence of TSH or PTH resistance with onset at 8 and 26 years." (PMID 39104441, 2024). "We retrospectively collected data from patients with PHP/iPPSDs (age, sex, genetic mutations, height, body mass index (BMI), PTH resistance, presence or absence of ectopic ossifications and brachydactyly)." (PMID 39267114, 2024). "PTH resistance and brachydactyly develop over time and become obvious by puberty." (PMID 33179219, 2021). "Moreover, after the exclusion of defects affecting the Gsα-cAMP signaling pathway, screening for such defects should be considered in the evaluation of specific iPPSDx patients showing brachydactyly, mental and/or behavioral defects and, unexpectedly, elevated PTH serum levels." (PMID 31555217, 2019). "Patient 3, in addition to resistance to PTH and TSH, showed brachydactyly, neuro-psychomotor retardation (IQ = 68–70%, need for extra help in school), stature growth slowing (less than the 25th percentile), strabismus and scoliosis." (PMID 30616679, 2019). "The pathophysiology of hearing loss remains elusive as hearing loss appears to be associated with ectopic ossification and short stature, but not with PTH resistance and brachydactyly." (PMID 39267114, 2024).
calcium metabolism disorders (8 papers, 2017 to 2025). "Elevated PTH indicates the risk of calcium-phosphorus metabolism disorders and vascular calcification." (PMID 40640722, 2025). "Aldosterone increases urinary calcium excretion, leading to a calcium metabolism disorder, thereby stimulating PTH secretion, and consequently causing bone loss." (PMID 38808106, 2024). "It is also established that calcium metabolism disorders stimulate parathyroid hormone (PTH) secretion and activation of bone resorption by osteoclast." (PMID 32163420, 2020). "Measurement of parathyroid hormone (PTH) is essential in the investigation and management of calcium metabolism disorders." (PMID 31379460, 2019).